RPL7P24 (ribosomal protein L7 pseudogene 24)
Synonyms: RPL7_8_586
Gene: Processed pseudogene on chromosome 5 (80,500,332 to 80,501,400, forward strand). Ensembl gene ENSG00000240003.
Diseases named in the same sentence as RPL7P24 in open-access papers:
RPL7P24 is named in the same sentence as 2 diseases in open-access papers, as found by Europe PMC text mining. Sharing a sentence is not in itself a finding about the gene and the disease. The quoted sentences say what the papers report.
Cirrhosis (1 paper, 2021). A chronic disorder of the liver in which liver tissue becomes scarred and is partially replaced by regenerative nodules and fibrotic tissue resulting in loss of liver function. "CALM1 and RPL7p24 were selected from the salmon modules, which correlated with treatment method, cirrhosis and BCLC classification." (PMID 34493740, 2021).
RPL7P24 also shares sentences with these, for which no sentence is quoted: tumor (1 paper).